PTPRD (protein tyrosine phosphatase receptor type D)
Diseases named in the same sentence as PTPRD in open-access papers (continued):
Sharing a sentence is not in itself a finding about the gene and the disease.
neurodevelopmental disorder (10 papers, 2021 to 2025). A behavioral and cognitive disorder with onset during the developmental period that involves impaired or aberrant development of intellectual, motor, or social functions. "PTPRD, a receptor protein tyrosine phosphatase genetically associated with neurodevelopmental disorders, regulates receptor tyrosine kinases to ensure appropriate numbers of neurons." (PMID 35811316, 2022). "Furthermore, in vitro inhibition of this signaling pathway by either pharmacological or RNAi strategies rescues neurogenic impairments observed in the absence of PTPRD, providing a direct link between PTPRD mutations and neurodevelopmental disorders." (PMID 34966732, 2021). "Foremost of the novel disease gene candidates we have identified is PTPRD, for which there are several lines of evidence supporting its role in neurodevelopmental disorders." (PMID 37056996, 2023). "PTPRD is a receptor protein tyrosine phosphatase, which is genetically related to neurodevelopmental disorders." (PMID 33920310, 2021). "Overall, results from various genetic studies are consistent with both major/oligogenic and modest/polygenic contributions of common and rare PTPRD variations in neurological, behavioural, and neurodevelopmental disorders." (PMID 34621295, 2021). "In the mouse, PTPRD was shown to regulate neurogenesis and mice lacking PTPRD showed impaired learning with enhanced hippocampal long-term potentiation, thus suggesting a role for PTPRD in neurodevelopmental disorders." (PMID 34621295, 2021).
brain disorder (5 papers, 2020 to 2025). A disease affecting the brain or part of the brain. "To complement this result, we analyzed the somatosensory cortex, another cortical region commonly disrupted in brain disorders associated with PTPRD mutations." (PMID 38890753, 2024). "Our results suggest a possible explanation for why variants in PTPRD result in brain disorders." (PMID 38890753, 2024). "One of the brain disorders in which PTPRD mutations have an important functional impact is RLS, also known as Willis–Ekbom disorder, which is characterized by symptoms including an urge to move, usually accompanied by uncomfortable sensations in the lower limbs." (PMID 34966732, 2021). "PTPRD genetic variations and its genomic location observed for each brain disorder are summarized." (PMID 34966732, 2021).
psychiatric disorder (3 papers, 2023 to 2025). A disorder characterized by behavioral and/or psychological abnormalities, often accompanied by physical symptoms. "As the four genes (CSMD1, PTPRD, LSAMP, and NPAS3), which remained significant also in the sex-specific analyses, have previously been implicated in other psychiatric disorders, pleiotropic effects could also be suggested." (PMID 39457114, 2024).
neurological disorders (2 papers, 2015 to 2018). "Mostly known as tumor suppressor gene, PTPRD was also discovered to have possible functional connections with neurological disorders and may have potential interaction with AD marker tau protein." (PMID 25859259, 2015).
blood disorders (1 paper, 2023). "SNPs within PTPRD may also be associated with hematological cancers or blood disorders in general." (PMID 37731134, 2023).
central nervous system disorder (1 paper, 2022). A disease involving the central nervous system. "Previous studies have reported an involvement of PTPRD in various central nervous system disorders, including addiction, but there have been few reports on the role of PTPRD in the peripheral nervous system." (PMID 35493326, 2022).
inflammation (1 paper, 2022). Aberrant reaction of the microcirculation characterized by movement of fluid and leukocytes from the blood into extravascular tissues. "SNPs in PNPLA3, TNF-α, AGTR1, IL-17A, IL-1B, PTPRD, and GATAD2A cause liver inflammation." (PMID 36000237, 2022).
metabolic disorders (1 paper, 2025). "By integrating adhesion and signaling, PTPRD emerges as a therapeutic entry point for neurodevelopmental, neuropsychiatric, and metabolic disorders." (PMID 41208653, 2025). "Finally, we outline outstanding questions, including the identification of synaptic phospho‐substrates of PTPRD and strategies for modulating its functions across neurodevelopmental, neuropsychiatric, and metabolic disorders." (PMID 41208653, 2025).
PTPRD also shares sentences with these, for which no sentence is quoted: trigonocephaly (6 papers); head and neck cancer (5); pancreatic cancer (3); adenocarcinoma (2); asthma (2); astrocytomas (2); clear cell renal carcinoma (2); craniosynostosis (2); diabetic retinopathy (2); laryngeal squamous cell carcinoma (2); lymphoma (2); metastatic melanoma (2); microcephaly (2); neurodegenerative disease (2); proliferative diabetic retinopathy (2); squamous cell carcinoma (2); alcohol use disorder (1); Anorexia (1); arrhythmogenic right ventricular cardiomyopathy (1); atrial fibrillation (1); autoimmune disease (1); bone sarcoma (1); bone tumors (1); brain cancer (1); brain tumours (1); cervical squamous cell carcinoma (1); childhood cancer (1); chondrodysplasia (1); chronic lymphocytic leukemia (1); cognitive decline (1).
A further 56 diseases each share a sentence with PTPRD in 1 paper.